TNF (tumor necrosis factor)
Diseases named in the same sentence as TNF in open-access papers (continued):
Sharing a sentence is not in itself a finding about the gene and the disease.
Insulin resistance (continued). "IL-17 is implicated in insulin resistance through multiple mechanisms, including the activation of inflammatory cells, such as macrophages, which subsequently secrete pro-inflammatory cytokines, such as TNF-α and IL-6." (PMID 40238306, 2025). "TNF-α and IL-6 may cause insulin resistance by suppressing the expression of GLUT-4 and insulin receptor substrate-1 (IRS-1) and activating the NF-κβ pathway." (PMID 40541974, 2025). "In the current study, we conducted a comparative analysis to evaluate the effects of TNFα, LPS, and PA or their combination on mitochondrial dysfunction and associated metabolic complications including oxidative stress damage and insulin resistance in 3T3-L1 adipocytes." (PMID 39269560, 2025). "Elevated levels of interleukin-6 and TNF-α in obese individuals could increase insulin resistance and cardiovascular risk." (PMID 40166678, 2025). "Interestingly, B lymphocytes are emerging players in promoting inflammation associated with insulin resistance and T2D by producing IgG antibodies, which in turn enhance local TNF-α and interferon-gamma (IFN-γ) production from macrophages and T cells." (PMID 40225857, 2025). "Interestingly in some literature, the competition to bind to glycoprotein receptor INS-R between insulin and TNF-α is also noted and cited as a cause of insulin resistance." (PMID 40136728, 2025). "Furthermore, TNF-α was the first proinflammatory cytokine linked to insulin resistance and T2DM pathogenesis as it decreased the expression of insulin-regulated glucose transporter type 4 (GLUT4), found mainly in adipocytes." (PMID 39837875, 2025). "This case-control study demonstrates that lower circulating IGF-1 levels are strongly associated with poor glycemic control in geriatric patients with T2DM, and are linked to greater insulin resistance, longer disease duration, inflammation (elevated TNF-α), and adverse lipid profiles." (PMID 41393761, 2025). "DMT2 and insulin resistance are associated with the overexpression of many inflammatory cytokines, such as tumor necrosis factor alpha (TNF-alpha), IL1 or IL6, which may affect the blood vessels and lead to CVD." (PMID 39940871, 2025). "Furthermore, the expression of TNF-α (Tnf gene), a pro-inflammatory cytokine associated with insulin resistance, was significantly increased in the HFD group compared with that in the ND group." (PMID 40869040, 2025). "Diet and gut microbiota, when altered, cause low-grade systemic inflammation that can lead to insulin resistance through increased levels of pro-inflammatory cytokines in the circulatory system, such as TNF-α, IL-6, β kinase inhibitor (IKKβ), and c-Jun N-terminal kinase (JNK)." (PMID 39997751, 2025). "Genetic variation within the TNF‐α locus may modulate individual differences in cytokine expression and, consequently, influence susceptibility to insulin resistance and T2DM." (PMID 41268160, 2025). "Furthermore, IL6, IL1B, and TNF are pro-inflammatory cytokines, which are associated with insulin resistance and the development of chronic inflammation." (PMID 40699728, 2025). "Visceral fat accumulation in PLHIV is linked to CD8+ T cell activation, insulin resistance, and higher levels of IL-6 and TNF-α, indicating that central obesity may play an important role in immune-metabolic interactions." (PMID 41305316, 2025). "Adipose tissue was the first site where TNF-α was linked to insulin resistance." (PMID 41463063, 2025). "Additionally, it inhibits nuclear factor-kappa B (NF-κB) signaling, leading to reduced expression of pro-inflammatory cytokines such as TNF-α and IL-6, which are implicated in insulin resistance." (PMID 40565030, 2025). "Furthermore, insulin resistance is also linked to dysregulated levels of adipokines, including adiponectin, leptin, tumor necrosis factor alpha (TNF-a), interleukin-1β, and interleukin-6, which have been linked to inflammation and fat accumulation." (PMID 40004054, 2025).
Insulin resistance (continued). "In contrast, VAT, situated around internal organs, displays higher lipolytic activity and greater secretion of pro-inflammatory adipokines such as tumor necrosis factor-alpha (TNF-α) and interleukin-6 (IL-6), contributing to insulin resistance and an increased risk of cardiometabolic diseases." (PMID 40491594, 2025). "Excess adipose tissue, particularly visceral fat, is metabolically active and acts as a source of pro-inflammatory adipokines, such as tumor necrosis factor-alpha (TNF-α) and interleukin-6 (IL-6), which are associated with systemic insulin resistance and endothelial dysfunction." (PMID 41301434, 2025). "Elevated IL-6 and TNF-α levels have been implicated in insulin resistance and chronic low-grade inflammation, which could exacerbate hyperglycemia and predispose women with GDM to developing T2DM postpartum." (PMID 40225013, 2025). "In addition, DNJ has anti-inflammatory and antioxidant activities, DNJ treatment reduced the levels of interleukin-6 (IL-6), tumor necrosis factor-α (TNF-α), and lipopolysaccharide (LPS) associated with insulin resistance." (PMID 40362022, 2025). "Therefore, our results suggest that TNFα-induced mitochondrial dysfunction in 3T3-L1 adipocytes is associated with insulin resistance." (PMID 39269560, 2025). "For example, pro-inflammatory cytokines, such as TNF - α, cause insulin resistance by promoting adipocyte catabolism and increasing serine/threonine phosphorylation of insulin receptor substrate-1 (IRS-1) through a variety of signalling pathways, including the IKKβ/NF-κB pathway." (PMID 40084146, 2025). "Glucose metabolism is also impaired with elevated TNF-α causing insulin resistance." (PMID 41141350, 2025). "Additionally, a high TyG index is associated with chronic inflammation, as insulin resistance induces adipose tissue to secrete pro-inflammatory cytokines, including interleukin-6 and tumor necrosis factor-α." (PMID 40606022, 2025). "However, numerous factors associated with the obese state have the capacity to induce insulin resistance in differentiated 3T3-L1 adipocytes including TNF-α, IL-6, dexamethasone, high insulin, glucosamine, and exposure to hypoxic environment." (PMID 39415617, 2024). "Chronic inflammation resulting from GD-induced increases in the levels of inflammatory factors, such as IFN-γ, IL-1β, and TNF-α in vivo, may contribute to insulin resistance and increase the risk of developing T2D by affecting insulin sensitivity." (PMID 39568808, 2024). "The increased risk of developing diabetes in HCV infections is associated with insulin resistance and a chronic inflammatory response due to an increased synthesis of pro-inflammatory cytokines, mainly tumor necrosis factor (TNF) alpha and interleukin-6 (IL-6)." (PMID 39457712, 2024). "Insulin resistance is linked to the buildup of visceral adipose tissue, which potentiates proinflammatory cytokines and adipokines, including IL-6, TNF-α, and leptin, enhancing lipolysis and stimulating the ovaries to produce androgens, leading to hyperandrogenemia." (PMID 39064282, 2024). "Notably, these pro-inflammatory factors, such as tumor necrosis factor-α and interleukin-6, were associated with an increased risk of insulin resistance and pancreatic β-cell dysfunction." (PMID 39301319, 2024). "In addition, elevated levels of IL-6 and TNF-α have been linked to systemic insulin resistance, which can potentially contribute to a poorer prognosis in BC patients." (PMID 39342063, 2024). "Further, direct cancer effects, such as cancer cachexia is associated with increased insulin resistance and impaired glucose tolerance, and cachexia-associated cytokines, such as tumor necrosis factor and interleukin- 6 are associated with the development of insulin resistance." (PMID 39020360, 2024). "Additionally, tumor necrosis factor-alpha (TNF-α), a major proinflammatory factor in the pathogenesis of sepsis, is associated with adverse outcomes and can induce insulin resistance." (PMID 38725059, 2024).
Insulin resistance (continued). "Interestingly, six of the cytokines elevated in 3n mice that were attenuated with the Ch+ diet (IL-1α, IL-1β, IFN-γ, TNF-α, IL-3, and IL-6) have been associated with the development of insulin resistance in T2D." (PMID 39683562, 2024). "Notably, our data align with previous knowledge, indicating that TNF-α-treated adipocytes can replicate key transcriptional changes associated with insulin resistance and metabolic shifts." (PMID 38820505, 2024). "Psoriasis promotes systemic inflammation which, in turn, promotes inflammation in adipose tissue, leading to the release of adipokines (resistin, leptin, and visfatin) and proinflammatory cytokines (IL-6 and TNF-α), which are directly linked to increased insulin resistance." (PMID 38473907, 2024). "Thus, the polymorphism rs1800629 of the TNF-α gene is associated with higher plasma levels of this cytokine, supporting its relationship with hypertension and insulin resistance." (PMID 39200288, 2024). "Furthermore, research has shown that C-3-Glu has the ability to safeguard adipocytes against insulin resistance caused by H2O2 or TNF-α via the inhibition of c-Jun NH2-terminal kinase activation." (PMID 38919261, 2024). "One mechanism of insulin resistance in patients with chronic liver disease is acquired growth hormone (GH-growth hormone) resistance, which is caused by an increase in pro-inflammatory cytokines, mainly TNF alpha." (PMID 39457712, 2024). "Therefore, both migraine and AD seem to share a common polymorphism which predisposes the carriers to higher levels of TNF-α, inflammation and most likely insulin resistance." (PMID 38913047, 2024). "Inflammation associated with TNF-α has been linked to the development of insulin resistance." (PMID 38362147, 2024). "It has been concluded that high glucose levels in patients with type 2 diabetes could inhibit the suppression of TNF-α by IL-10 because of its disrupted messaging pathway which can cause insulin resistance." (PMID 38164478, 2024). "Additionally, ROS can trigger inflammation, causing the release of TNF-α, leptin, and GH, and this cascade ultimately results in insulin resistance, accelerated muscle breakdown, and the loss of muscle mass." (PMID 39286235, 2024). "The insulin resistance of hepatocytes is caused, among other things, by exposure to increased concentrations of free fatty acids and hyperinsulinemia, and pro-inflammatory cytokines, such as TNF, intensify this process." (PMID 38399444, 2024). "Adipocyte cell size has been shown to be an independent predictor of insulin resistance and risk for type 2 diabetes, which was associated with the expression and secretion of important inflammatory molecules (such as TNFα and IL-6), further supporting the proinflammatory state." (PMID 38347470, 2024). "Excess visceral fat becomes dysfunctional and releases adipokines and inflammatory cytokines, such as tumor necrosis factor-alpha (TNF-α) and interleukin-6 (IL-6), which cause chronic low-grade inflammation and insulin resistance-key characteristics of type 2 diabetes." (PMID 39650923, 2024). "In turn, pro-inflammatory cytokines (TNF-α and IL-6) have the ability to induce the expression of resistin, which is directly related to insulin resistance and is associated with the activation of inflammatory processes through a pathway dependent on nuclear factor κB (NF-κB)." (PMID 39201576, 2024). "CRP and TNF-α have been associated with insulin resistance and atherosclerosis." (PMID 38566090, 2024). "Insulin resistance is caused by the enlargement of adipose tissue cells and the increased release of pro-inflammatory substances such as tumor necrosis factor (TNF)-α and interleukin (IL)-6, together with progressive adipose tissue infiltration by immune cells." (PMID 39125666, 2024).
Insulin resistance (continued). "In the last 24h of differentiation, the spheroids were treated with 2.5 nM of TNF-α, which is a cytokine associated with inflammatory processes, and that had been linked to the induction of insulin resistance in murine adipocytes by reducing the transcriptional activity of GLUT4 gene." (PMID 38820505, 2024). "CRP and TNF-α were associated with insulin resistance and ceramide production, which may be associated with reduced LV function." (PMID 38566090, 2024). "NF-κB, a transcription factor influenced by TNF-α, may also contribute to insulin resistance through a specific mechanism linked to its significant upregulation of inflammatory interleukins (e.g., IL-1β, IL-6) upon activation." (PMID 39911236, 2024). "Moreover, high concentrations of TNF, IL-1β and IL-6 in circulation cause insulin resistance in hepatocytes and skeletal muscle cells and inhibit insulin production by the pancreas." (PMID 39107476, 2024). "In addition, the strong associations of ME1 with leptin, PPAR-γ, and TNF-α support significant role(s) for hepatic ME1 in predisposition for insulin resistance and type II diabetes mellitus." (PMID 37047583, 2023). "Interventions that recapitulate causes of insulin resistance in humans, including hyperinsulinemia (chronic incubation with insulin, CI), chronic inflammation (TNF-α) and Cushing’s syndrome/inflammatory steroids (dexamethasone, DEX) have been used to model insulin resistance in 3T3-L1 adipocytes." (PMID 36283703, 2023). "Some studies have also suggested that low SMD is associated with disease severity, which might be a result of insulin resistance, proinflammatory mediators (such as IL‐6 and TNF‐α), vitamin D deficiency and metabolic acidosis." (PMID 37722854, 2023). "Diabetes and insulin resistance are linked to a high level of TNF-α in the blood." (PMID 37853419, 2023). "Burn-induced increase in TNF-α concentrations can increase the rate of lipolysis and hence production of free fatty acids, which can contribute to the hyperglycemia and increased insulin resistance associated with post burn injury." (PMID 37333522, 2023). "Excess visceral adiposity is associated with altered secretion of bioactive peptides like adiponectin, leptin, interleukin-6, and tumor necrosis factor-α, predisposing to inappropriate inflammatory responses, insulin resistance, increased sympathetic activity and RAAS activation." (PMID 36973671, 2023). "Notably, TNF-α levels are correlated with the degree of adiposity and the associated insulin resistance." (PMID 37798684, 2023). "Insulin resistance and adipose tissue hyperplasia, on the other hand, are considered inflammatory states that are associated with elevated proinflammatory mediators and cytokines, e.g., TNF-α and IL-6." (PMID 37764820, 2023). "Additionally, IL-1 has been demonstrated to be implicated in pancreatic cell destruction, whereas tumor necrosis factor seems to be a critical molecule in peripheral insulin resistance and IL-6 has a direct influence on glucose and lipid metabolism." (PMID 36674154, 2023). "TNF-α has also been associated with the pathogenesis of insulin resistance and diabetes mellitus." (PMID 36939969, 2023). "In light of this, IL-18, alongside TNF-α, may be implicated in the pathogenesis of insulin resistance." (PMID 37049621, 2023). "In T2D, there is a disturbance in the ratio between Th1/Th2 in favor of the first, which produces cytokines such as INFγ and TNFα and suppresses Th2 with its Tregs cytokines; this phenomenon is caused by insulin resistance and oxidative stress and leads to coronary artery disease." (PMID 38137918, 2023). "Cytokines associated with blood sugar control include TNF-α, IL-6, and IL-10, which may have insulin receptor substrates (IRSs) that are converted to serine, which leads to insulin resistance." (PMID 38098816, 2023). "NF-κB and TNF α were found to be associated with insulin resistance." (PMID 37511575, 2023).
Insulin resistance (continued). "The increased risk of developing DM may be due to an inflammatory condition associated with RA, with the over-activation of TNFα and IL-6 pathways contributing to an increase in insulin resistance and causing DM." (PMID 36983150, 2023). "Alternatively, a reduction in IκBα might cause an increased translocation of NF-κB into the nucleus, increasing the transcription of several inflammatory cytokines, such as tumor necrosis factor-α, associated with insulin resistance." (PMID 36998473, 2023). "The reduction in glucose uptake and downregulation of adiponectin in the TNF-α-induced 3T3-L1 adipocytes might be associated with insulin resistance." (PMID 37367060, 2023). "Insulin resistance may cause the upregulation of IL-6, TNF-α, and myostatin and the downregulation of IL-15, FGF-21, and irisin levels." (PMID 37298440, 2023). "M1 macrophages secrete cytokines, such as TNF-α, that can cause adipocyte insulin resistance." (PMID 37571282, 2023). "In addition, lean NAFLD is associated with lower levels of proinflammatory cytokines (e.g., interleukin 6 and tumor necrosis factor alpha), which are known as a risk factors for cardiovascular disease, metabolic syndrome, and insulin resistance." (PMID 36198747, 2022). "We postulate that the phylum Firmicutes generates TNF-α-driven systemic inflammation and consequent insulin resistance may cause RIF." (PMID 35413875, 2022). "CRP and TNF-α are associated with insulin resistance and atherosclerosis." (PMID 35548430, 2022). "Further, high TNF-alpha levels are associated with insulin resistance." (PMID 35203477, 2022). "Both TNF-α and IL-6 have been suggested to be associated with insulin resistance in T2DM subjects." (PMID 35083338, 2022). "This reduction of adipogenesis by Sirt3 inhibitor was associated with increased proinflammatory cytokines including IL6, resistin, and TNF, suggesting Sirt3 downregulation might increase the risk of insulin resistance and metabolic abnormalities." (PMID 35409099, 2022). "Importantly, TNF-α, a cytokine produced in the adipose tissue, is associated with insulin resistance." (PMID 35458670, 2022). "Inflammatory markers IL-6 and tumor necrosis factor alpha (TNF-α) are linked to insulin resistance, another metabolic abnormality which may be induced in PCOS." (PMID 36117653, 2022). "Based on gene count, we identified the top 29 pathways in the KEGG pathway enrichment analysis, which were associated with insulin resistance and inflammation, such as TNF signaling, PI3K-Akt signaling, MAPK signaling, HIF-1 signaling, estrogen signaling, cAMP signaling, and mTOR signaling pathways." (PMID 35052852, 2022). "In addition, the chronic inflammation of adipose tissue caused by hyperinsulinemia and insulin resistance in obese individuals promotes the secretion of proinflammatory cytokines, such as tumor necrosis factor alpha (TNFα) and interleukin 6 (IL-6)." (PMID 35159342, 2022). "Insulin resistance is a hallmark of the metabolic syndrome associated with obesity, TNF-α, IL-6, adiponectin, resistin, and free fatty acids, all of which are contained in visceral fat, may have a role in the development of insulin resistance." (PMID 35159388, 2022). "However, further research is required to determine how AIP1 regulates TNF-α signaling pathways and its association with insulin resistance." (PMID 35712257, 2022). "In the case of severe COVID-19, insulin resistance may be caused by elevated levels of tumor necrosis factor-alpha (TNFα) and interleukin-6 (IL-6)." (PMID 36548203, 2022). "In fact, studies based on dietary surveys have associated a low intake of exogenous AGEs with lower insulin resistance, TNF alpha levels, peripheral cell mononuclear cells and leptin concentration, as well as higher adiponectin, which ultimately means less proinflammatory activity." (PMID 36615860, 2022).